BCL6 (BCL6 transcription repressor)
Diseases named in the same sentence as BCL6 in open-access papers (continued):
Sharing a sentence is not in itself a finding about the gene and the disease.
tumor (continued). "Moreover, as MC38 and B16F10 growth curves were comparable in Bcl6fl/fl Mb1-cre and Bcl6fl/fl mice, BCL6 insufficiency or derepression of its antagonized targets, such as BLIMP in B cells, likely does not affect tumor immunity." (PMID 41145211, 2026). "Tumor cells typically express CD20, CD5, and Cyclin D1, while lacking CD10 and Bcl-6." (PMID 41585338, 2026). "The tumor cells express pan B-cell markers and show a non-GCB phenotype, mostly CD10-/BCL6+/MUM1+." (PMID 40941006, 2025). "The tumor cells show a B-cell phenotype with expression of the transcription factors BOB1 and OCT2 and often a non-GCB phenotype with lack of CD10 expression but expression of MUM1, BCL6, and MEF2B." (PMID 39707053, 2025). "In anti-tumor proliferation experiments, WK369 inhibited cell proliferation in a variety of OV cells that highly expressed BCL6, but had little effect on normal cells that were independent of BCL6." (PMID 38169532, 2024). "Interestingly, T cell exhaustion, marked by the expression of PD1 and Tim3, was not affected by Bcl6, which indicates that Bcl6 does not affect T cell exhaustion in HCC tumor." (PMID 38956432, 2024). "By IHC, the tumor cells were positive for CD20 and BCL‐6 and negative for CD10." (PMID 37206267, 2023). "The tumor cells were negative for CD10, BCL6, CD5, and SOX11." (PMID 37555980, 2023). "A majority (67–96%) of cases are of an activated B-cell (ABC)/non-germinal center B-cell (non-GCB) subtype where the tumor cells are either (i) CD10-negative, Bcl-6-negative or (ii) CD10-negative, Bcl-6-positive, and MUM1-positive by immunohistochemistry using the Hans algorithm." (PMID 33322508, 2020). "It is not known whether the presence of BCL-6 is related to the difference in morphology between AITL and TFH-PTCL-NOS, or if it has a role in a difference in the etiopathogenesis of these two tumor subgroups." (PMID 29662631, 2018). "The tumor showed the proliferation of large lymphoid cells with centroblastic morphology, which were positive for CD138, CD38, CD56 and MUM-1, and negative for CD20, CD79a, BCL-6 and HHV8." (PMID 26543559, 2015). "The tumour from the patient whose serum was used for library screening was negative for CD10 and BCL-6 and positive for MUM1, suggesting that the patient had a poor prognosis non-germinal centre-derived subtype of DLBCL; this is consistent with the short survival time." (PMID 15162151, 2004). "As lack of BCL6 in activated CD8 T cells stimulated the GLUT3-mediated glycolysis pathway, ultimately retarding CD8+ T-cell exhaustion and enhancing their effector functions, we surmise that this mechanism explains the T-cell dependence of Fx1 drug-induced tumor resistance." (PMID 41145211, 2026). "In this study, we found that the induction of Bcl6 expression was strictly confined to tumor-infiltrating Treg cells, and the deletion of Bcl6 in Treg cells specifically repressed the function of this population, leaving systemic Treg cells (outside of TME) that do not express Bcl6 intact." (PMID 32477338, 2020).
cancer (168 papers, 2008 to 2026). A tumor composed of atypical neoplastic, often pleomorphic cells that invade other tissues. "Overall, a low level of BCL6 mRNA in human cancer samples is associated with better outcomes, but high expression of BCL6 is specifically observed in cytotoxic CD8 T cells." (PMID 41145211, 2026). "Molecularly, the overexpression of Tcf7, Bcl6, β-catenin, and possibly other genes can contribute to cancer progression and the risk of relapse." (PMID 40057636, 2025). "Cancer-associated mutant forms of FBW7β (R385H and R385C) corresponding to FBW7α (R465H and R465C) displayed a reduced ability to promote BCL6 degradation." (PMID 38485719, 2024). "Thereafter, we investigated the underlying mechanisms by which BCL6 inhibition blocked KRAS-mutant cancer growth." (PMID 36377663, 2022). "The results of this study provide a novel mechanistic insight into the oncogenic roles of NAC1, and underlines the importance of developing NAC1/BCL6-targeted cancer therapy." (PMID 32412910, 2020). "The genetic loss of BCL6 resulted in an inhibition of cancer cell proliferation and an arrest in cell cycle progression at the G1 transition with significant induction of apoptosis." (PMID 32180900, 2020). "And as shown in previous studies, BCL6 is implicated in regulating multiple molecules that involved in malignant phenotype of cancers." (PMID 30420967, 2018). "Inhibition of methylation and histone deacetylation in these cancer cells causes over expression of miR-127 and related down regulation of the target BCL6, a bona fide protooncogene." (PMID 22900969, 2012). "Some researches suggested that targeting the BTB/POZ domain of BCL-6 caused apoptosis and cell cycle arrest, providing a novel approach for cancer therapy." (PMID 21702992, 2011). "The use of inhibitors of methylation and histone deacetylation in these cancer cells causes over expression of miR-127 and related down regulation of the target BCL6 (NM_138931), a bona fide proto-oncogene." (PMID 18478077, 2008). "(A) Association between BCL6 upregulation with ETO sensitivity in various cancer cell lines." (PMID 35503721, 2022). "Unlike KRAS G12C–selective inhibitors, targeted inhibition of BCL6 might be effective in the majority of KRAS-mutant cancer subtypes and even in tumors harboring NRAS mutations." (PMID 36377663, 2022). "In addition, outside those mentioned, a group of transcription factors, which dysregulation has been widely associated with cancer phenotype was identified, including DEGs such as BCL6, DDIT3, GADD45A, HMGA2, and ID2." (PMID 35359411, 2022). "Currently, it is unclear that the reason for BCL6 upregulated in cancer tissues, the constitutive expression caused by translocation might partly explain the overexpression of this gene in cancer tissues." (PMID 30420967, 2018). "Numerous studies have revealed that BCL6 is associated with cancer metastasis." (PMID 25009651, 2014). "Our study supports observations from the study of Chen Dong and colleagues that BCL6 limits T-cell function against cancer." (PMID 41145211, 2026). "In a mouse model of ovarian cancer, WK369 prevented cancer growth and suppressed BCL6-driven AKT and MEK/ERK signaling, which are intracellular pathways linked to cancer progression." (PMID 41246349, 2025). "The structural properties of BCL6 make it a valuable target for the development of novel and selective anti-cancer therapies." (PMID 40821118, 2025). "A number of small molecules that inhibit peptides and BCL6 in cell and animal models of cancer have been developed." (PMID 40821118, 2025). "A recent study showed BCL6, whose translocation is a BN2 hallmark, requires LSD1 for lymphomagenesis and the LSD1 inhibitor seclidemstat is in cancer clinical trials (NCT04734990, NCT03600649)." (PMID 39894894, 2025). "Extending these studies to additional cancer models will elucidate resveratrol’s role in modulating BCL6 activity across diverse malignancies, potentially expanding its clinical applications." (PMID 39815148, 2025).
cancer (continued). "Esm1 recombinant protein decreased T cell adhesion to ICAM-1, and cancer cell medium from Esm1 overexpression group inhibited T cell adhesion compared to Bcl6 knockout control group." (PMID 38956432, 2024). "This control serves to suppress the IL-2/STAT5 pathway, offering insights into the functional interplay between TGF-β and Bcl6 in cancer immunity, as well as providing potential targets for cancer immunotherapy." (PMID 38780677, 2024). "It has been suggested that this role for BCL6 is part of an evolutionarily conserved stress response that enables cancer cells to adapt to stressors, including therapeutic agents." (PMID 39456751, 2024). "Collectively, we uncovered an unappreciated paracrine mechanism of how Bcl6 promotes cancer progression and highlighted the role of CD4+T cells in HCC immune surveillance." (PMID 38956432, 2024). "In contrast with the controls, the level of BCL6 in the UC and cancer patients dramatically increased (P < 0.0001)." (PMID 39582536, 2024). "To analysis the expression of BCL6 in HCC tissue, we firstly applied data from The Cancer Genome Atlas (TCGA) to determine the pan-cancer expression of BCL6 in different cancer types." (PMID 38956432, 2024). "IL-6 signaling pathway and IFNγ response were most significantly enriched in Bcl6 knockout cancer cells." (PMID 38956432, 2024). "In accordance with TCGA data, western blotting revealed that for most HCC samples, BCL6 was elevated in the cancer tissue compared to the normal adjacent tissue." (PMID 38956432, 2024). "Then by using ICAM-1 adhesion assay, we found that cancer cell-derived conditioned medium from Bcl6 knockout group increased T cell adhesion to ICAM-1 coated plate compared to wild type cancer medium." (PMID 38956432, 2024). "For function, we also found that even though CD4+T cells have higher cytotoxicity than CD8+T cells towards HCC, blockade of CD8 also improved cancer cell progression in Bcl6 KO group." (PMID 38956432, 2024). "Our research expanded the mechanism of BCL6 in cancer progression, and highlighted the role of CD4+T cells in HCC immune surveillance." (PMID 38956432, 2024). "Our findings uncovered an unappreciated paracrine mechanism how cancer cell-derived BCL6 assists cancer cell immune evasion, and highlighted the role of CD4+T cells in HCC immune surveillance." (PMID 38956432, 2024). "We found that BCL6 is elevated in many cancer types including GBM, KIRC, SARC and LIHC (P = 0.0786)." (PMID 38956432, 2024). "By redirecting the catalytic activity of CDK9 to BCL6-targeted loci, CDK-TCIPs induce selective killing of BCL6-overexpressing cancer cells." (PMID 39702508, 2024). "In the pan-cancer B-cell Atlas, the Gao team described and investigated the role of BCL6 in the TME of CRC." (PMID 39582536, 2024). "Mechanistically, BCL6 decreases cancer cell expression of pro-inflammatory cytokines and T lymphocyte chemokines such as IL6, IL1F6, and CCL5." (PMID 38956432, 2024). "BCL6 has been separately demonstrated to inhibit the effectiveness of cancer therapies, with BCL6 often found to be upregulated by the therapeutic agent." (PMID 39456751, 2024). "Mechanistically, BCL6 suppress pro-inflammatory cytokines expression by HCC cancer cells and promoted the expression of immune suppressive protein ESM1, which was reported to be antagonist of ICAM-1 in binding to T cell surface protein LFA-1." (PMID 38956432, 2024). "Top expressed cancer-implicated gene targets for each TF converged on notable genes involved in cell signaling (SMAD3, PTPRJ), BCL6 regulation (FBXO11, BCOR), and transcriptional regulation (RUNX1, ERG, CUX1)." (PMID 38116118, 2023). "Left vertical axis, IC50s of etoposide in different cancer cell lines; right vertical axis, relative BCL6 protein levels compared with that of the control group; horizontal axis, cancer cell lines." (PMID 35503721, 2022). "(F) BCL6 protein expression levels in different cancer cell lines in response to various genotoxic agents." (PMID 35503721, 2022).
cancer (continued). "In this study, we loaded BCL6 siRNA in iRGD-Exo for delivery of BCL6 siRNA into bloodstream and cancer cells in vivo precisely." (PMID 35982974, 2022). "Due to the oncogenic driver role of BCL6 in cancer, many compounds were designed to interfere with its transcriptional repressor activity and subsequently attenuate the oncogenic effects of BCL6." (PMID 35906392, 2022). "BCL6 pharmacological inhibitors that block the interaction between BCL6 and BCoR/NCoR/SMRT exert cytotoxicity toward BCL6-addicted cancer cells." (PMID 36377663, 2022). "In BC cells, the oncogene BCL6 and cancer progression-related genes ROCK2 and CDH11 have been identified as targets of miR-127 in BC." (PMID 36371182, 2022). "BCL6 normally acts as a corepressor in B cells, but in the pathway leading to cancer, one of its natural ligands disrupts its corepressor function, and if this trend continues, it will lead to the proliferation of B cells and cancer." (PMID 35346211, 2022). "In summary, our study unveils a distinct macrophages subpopulation that was driven by Bcl6 to persistently promote cancer progression." (PMID 36542153, 2022). "We observed a striking association between the activation of pro-inflammatory signals and BCL6 induction in chemoresistant cancer cells." (PMID 35503721, 2022). "The GLVATVKEAGRSIHEIPREEL peptide has been produced as a synthetic ligand for BCL6 (an important transcription factor in multiple pathways), and the results suggest that it is an effective treatment for cancers such as lymphoma." (PMID 35346211, 2022). "Collectively, these results demonstrate that BCL6 expression correlates with poor patient survival in KRAS-mutant cancers, including LUAD." (PMID 36377663, 2022). "We further determined the association between BCL6 expression and survival outcomes of patients with KRAS-mutant cancers (n = 689) using TCGA database." (PMID 36377663, 2022). "Although BCL6 depletion led to growth arrest in all tested cell lines, KRAS-mutant cancer cells were more susceptible to BCL6 inhibition than WT cancer cells." (PMID 36377663, 2022). "We further demonstrated that Bcl6 played a central role in coordinating the transcriptional, epigenetic and metabolic pathways to control SMMs commitment underpinning cancer progression." (PMID 36542153, 2022). "The cancer-related genes BCL6, FANCC, PICALM and SGK1 were included among the target genes of the 64 TFBSs." (PMID 34316701, 2021). "BCOR is likely to be a crucial mediator of BCL6 function in these cancers, whereas BCL6 can coordinate the actions of the BCOR polycomb-like complex (BCOR, PCGF1, RING1B, and KDM2B) to potently repress target genes." (PMID 33468080, 2021). "To evaluate if BCL6 is expressed also in NSCLC we investigated BCL6 mRNA levels in 31 different cancer types using the cancer genome atlas (TCGA) PanCancer data set." (PMID 32234966, 2020). "To investigate if combination therapy targeting EGFR and BCL6 would be more effective in killing cancer cells than monotherapy we treated all three cell lines with gefitinib and FX1, alone or in combination, and evaluated survival using clonogenic assay." (PMID 32234966, 2020). "Co-staining BCL6 with GBM cancer stem cell markers such as CD133, integrin a6, notch or IL8 receptors would support this." (PMID 32320427, 2020). "Constitutive BCL6 expression within GC B-cells leads to the development of DLBCL in mice that mimics that observed in patients suggesting that BCL6 is sufficient to initiate cancer." (PMID 32180900, 2020). "miR-127 is primarily involved in cancer pathologies by regulating cell proliferation and senescence through the oncogene BCL6." (PMID 33089155, 2019).
cancer (continued). "Using this tool, we also discovered that cancers scoring higher for BCL6 activity, a transcription factor expressed by T-fh cells, have a significantly better prognosis." (PMID 31227749, 2019). "Bcl-6 protein, a transcriptional repressor, is a critical regulator of germinal centers and involves in the development and progression of cancers with uncertain mechanism and is relevant to MAPK signaling process." (PMID 32038276, 2019). "We found that ectopic ZBTB28 expression did inhibit luciferase reporter activities of BCL6-promoter and BCL6 mRNA expression levels in both 293T and carcinoma (HONE1, A549) cells." (PMID 31754389, 2019). "Immunofluorescence assay demonstrated that ZBTB28 was co-localized with BCL6 in nuclei of carcinoma cells." (PMID 31754389, 2019). "As a result, we identified eight common mutated genes (EBAG9, MTDH, ATP6V1C1, OPA1, ATCL6A, BCL6, SENP5, KRAS) in the three different cancer types and used them as cross-cancer biomarkers to perform an integrative network analysis." (PMID 29459674, 2018). "The known role of miR-339a is limited to cancer-related functions such as the down-regulation of BCL6 expression." (PMID 26889380, 2016). "Patients with low- and medium-grade carcinomas expressed the Bcl-6 gene to high levels compared to patients with high-grade disease (p < 0.0001)." (PMID 27237631, 2016). "The correlation of expression of each of these polarity and cytoskeletal genes in each dataset revealed that there were significant correlations (P<0.05) for several cytoskeletal or polarity regulatory genes with Bcl6 or ZBTB7A in several cancer types." (PMID 26187947, 2015). "Recurrent dysregulation associated with cis-regulatory mutations was also observed as exemplified in the promoter of BCL6 along with a potential cascading effect on interactors known to be involved in cancer development." (PMID 25903198, 2015). "Overall, the role of BCL6 protein in human cancers other than in the lymphoid system remains to be determined." (PMID 24917186, 2014). "Previously, Saito and his colleagues also reported specific activation of microRNA-127 with downregulation of the proto-oncogene BCL-6 by chromatin-modifying drugs in human cancer cells." (PMID 25477702, 2014). "Recently, BCL6 protein was also shown to be highly expressed in various human cancers other than malignancy in the lymphoid system." (PMID 24917186, 2014). "B-cell lymphoma 6 (BCL6) protein, an evolutionarily conserved zinc finger transcription factor, showed to be highly expressed in various human cancers in addition to malignancies in the lymphoid system." (PMID 24917186, 2014). "Of 15 PDAC cases, 13 (87%) comprised inflammatory infiltrate; 11 of these (85%), including four cancers with PanINs, showed BCL6 immunoreactivity." (PMID 23372777, 2013). "BCL6 was highly expressed in cyclin D2-negative cases and was remarkably reduced in cyclin D2-positive cancer cases in the HB-EGF-positive group." (PMID 19337254, 2009). "Increasing studies suggest that BCL6 works as an oncogene in human cancer." (PMID 41145211, 2026). "Because memory T cells or exhausted T cells are generated from effectors, it is unclear whether BCL6 has any role in the differentiation of T-cell exhaustion, its functional window period, or whether it can be used as a target of cancer treatment." (PMID 41145211, 2026). "Targeting BCL6 has increased cancer cell sensitivity to chemotherapy, suggesting its inhibition could overcome resistance in solid tumors." (PMID 39796244, 2025). "First, the effect of BCL6 on HCC cancer cell proliferation also contribute to HCC development." (PMID 38956432, 2024). "The level of BCL6 in the UC patients was greater than the cancer patients (P < 0.0001)." (PMID 39582536, 2024). "Whether cancer cell derived BCL6 participates in cancer immune evasion and whether BCL6 plays a role in HCC progression has not been studied." (PMID 38956432, 2024).